CMKLR1 (chemerin chemokine-like receptor 1)
Diseases named in the same sentence as CMKLR1 in open-access papers (continued):
Sharing a sentence is not in itself a finding about the gene and the disease.
melanoma (5 papers, 2018 to 2025). A malignant, usually aggressive tumor composed of atypical, neoplastic melanocytes. "Furthermore, the presence of CMKLR1 in melanoma cells is necessary to induce the inhibition of tumor growth and alteration in cell composition of immune infiltrates." (PMID 34946244, 2021). "Further experiments showed that host expression of CMKLR1 was necessary for inhibited tumor growth, since chemerin-expressing mouse melanoma grew faster than control B16 tumors in CMKLR1-negative mice." (PMID 30555465, 2018). "Additionally, mregDC also up-regulated the interaction of RARRES2 (chemerin) and CMKLR1 with non-classical monocytes, and indeed chemerin has been reported to act as a tumor suppressive cytokine in mouse melanoma models by recruiting innate immune cells into the TME59." (PMID 40890106, 2025).
ovarian carcinoma (5 papers, 2019 to 2025). A malignant neoplasm originating from the surface ovarian epithelium. "Association of chemerin and CMKLR1 in ovarian cancer tissue with overall and progression-free survival." (PMID 36900088, 2023). "First, results showed that mean levels of chemerin and CMKLR1 were elevated in ovarian cancers with higher cytoplasmic ERβ expression when compared to the lower expressing subgroup (p = 0.0143 and p = 0.0133, respectively)." (PMID 36900088, 2023). "Mean protein levels of CMKLR1 were increased in ovarian cancer specimens with higher expression of the proliferation marker Ki67 (p = 0.0304)." (PMID 36900088, 2023). "In conclusion, with regard to tumor expression of chemerin receptors, this adipokine is suggested to exert a tumor-suppressive role in ovarian cancer via binding to CMKLR1 and CCRL2." (PMID 31370263, 2019). "Moreover, it was acknowledged that an augmented level of CMKLR1 in ovarian cancer specimens improved the outcome in individuals with ovarian cancer." (PMID 40076482, 2025). "In a healthy ovary, chemerin induces apoptosis of ovarian granulosa cells by binding to CMKLR1, suggesting that this phenomenon may also be present in ovarian cancer." (PMID 40076482, 2025). "Subsequently, mean protein levels of chemerin and CMKLR1 in ovarian cancer subgroups were compared with high vs. low expression of the ovarian cancer markers, cancer-related proteins, and components of estrogen signaling pathways that were analyzed in this study." (PMID 36900088, 2023). "Chemerin protein and its receptor CMKLR1 were demonstrated to be abundantly detectable by immunohistochemistry in ovarian cancer tissues and to positively correlate with intratumoral expression of PR, ERβ and ERRs, corroborating interaction with estrogen signaling pathways as previously suggested." (PMID 36900088, 2023). "The observation that chemerin was able to induce apoptosis in ovarian follicles via CMKLR1 raises the question, whether the same effect could be present in ovarian cancer." (PMID 31370263, 2019). "In the current study, protein levels of chemerin and CMKLR1 were assessed by immunohistochemistry of tissue microarrays (TMA), including tissues of 208 ovarian cancer patients." (PMID 36900088, 2023). "The prolonged OS of patients with high expression of CMKLR1 and CCRL2 clearly suggested an anti-tumoral effect of serum chemerin being activated in ovarian cancer tissue." (PMID 31370263, 2019). "Importantly, higher intratumoral expression of CMKLR1 has a beneficial effect both on overall survival (OS) (p = 0.002, HR = 0.8 (0.7–0.92)) and on progression-free survival (PFS) (p = 0.026, HR = 0.86 (0.76–0.98) in ovarian cancer patients." (PMID 36077645, 2022). "RARRES2 levels negatively, whereas CMKLR1 levels positively influenced both OS and progression-free survival (PFS) of ovarian cancer patients, and GPR1 and CCRL2 levels did not affect patients’ OS or PFS." (PMID 36009457, 2022). "First, we characterized the employed ovarian cancer cell lines OVCAR-3, OAW-42 and SK-OV-3 with regard to their expression of the receptors CMKLR1 and GPR1, which are known (unlike CCRL2) to affect intracellular signaling and thus are relevant for this in vitro study." (PMID 36077645, 2022).
polycystic ovary syndrome (5 papers, 2016 to 2023). A disorder that manifests as multiple cysts on the ovaries. "Enhanced ovarian chemerin by hyperandrogenemia seems to recruit the CMKLR1-positive macrophages to influence the immune microenvironment of ovaries." (PMID 36009457, 2022). "The results of this study also support the concept that in PCOS, hyperandrogenemia increases chemerin expression promoting the recruitment of CMKLR1+ monocytes, deregulating the immunological niche of ovaries." (PMID 36289764, 2022). "Compared with WT controls, CMKLR1−/− mice had significantly reduced clinical signs to the dihydrotestosterone-induced polycystic ovary syndrome, experimental autoimmune encephalomyelitis, and chronic obstructive pulmonary disease." (PMID 29279348, 2018). "It has been implicated that CMKLR1 may signal through BMP4 to regulate estrogen and progesterone secretion in polycystic ovary syndrome, although this mechanism has not been fully delineated." (PMID 29279348, 2018).
psoriasis (5 papers, 2015 to 2025). An autoimmune condition characterized by red, well-delineated plaques with silvery scales that are usually on the extensor surfaces and scalp. "CMKLR1 antagonists are increasingly viewed as therapeutic modalities for a variety of diseases (e.g., psoriasis, metabolic disorders, and multiple sclerosis)." (PMID 36467705, 2022). "CMKLR1 is also up-regulated in dermal MSCs from psoriasis patients." (PMID 35723360, 2022). "We observed the upregulation of CMKLR-1, COL8A-1, NETO-2, NRK, SYTL-2, and SULF-2 in dermal mesenchymal stem cells derived from patients with psoriasis at both mRNA and protein level, however, a significant downregulation of SFRP-2 between two groups." (PMID 30760317, 2019). "We observed significant increases in protein expression of CMKLR-1, COL8A-1, NRK, and SYTL-2 in DMSCs from patients with psoriasis compared with those from healthy donors, whereas the expression level of SFRP-2 was obviously decreased." (PMID 30760317, 2019).
steatosis (5 papers, 2014 to 2023). Increased lipid within the cytoplasm of cells. "Some believe the upregulated CMKLR1 alleviated steatosis while others revealed the opposite findings." (PMID 36624417, 2023). "In line with this, the same investigators showed that Cmklr1-/- mice have reduced steatosis on a low fat diet." (PMID 24781986, 2014). "The alleviating effect on steatosis are only notified in mice with less weight gain, indicating that there is no sufficient evidence to reveal that intestinal chemerin/CMKLR1 pathway is involved in gut-liver axis hence the progress of NAFLD." (PMID 36624417, 2023). "The tumor chemerin and CMKLR1 protein expression were not related to steatosis, inflammation and fibrosis grades." (PMID 36979716, 2023). "The CMKLR1 protein was not related to tumor size, steatosis grade, fibrosis grade, or age." (PMID 36979716, 2023). "CMKLR1 protein was not related to tumor size, steatosis score, inflammation, or fibrosis grade." (PMID 36979716, 2023). "The CMKLR1 protein in the HCC tissues of the female patients was not related to age, steatosis score, inflammation, or fibrosis grade." (PMID 36979716, 2023).
type 2 diabetes (5 papers, 2015 to 2022). "Therefore, the association of CMKLR1 with type 2 diabetes and/or hypercholesterolemia has to be evaluated in different cohorts using patients who ideally do not suffer from NASH." (PMID 27548138, 2016). "In males, CMKLR1 expression tended to be higher in the 10 patients with type 2 diabetes (p = 0.058)." (PMID 27548138, 2016). "Liver CMKLR1 mRNA tended to be higher in type 2 diabetes patients of both genders and in hypercholesterolemic women." (PMID 27548138, 2016). "CMKLR1 mRNA was still associated with inflammation, fibrosis and NASH score when those suffering from type 2 diabetes were excluded." (PMID 27548138, 2016). "Our findings are consistent with chemerin, through its receptor CMKLR1, having beneficial effects in type 2 diabetes, which is contrary to the opinion of some other authors." (PMID 25699203, 2015). "CMKLR1 mRNA was elevated in the 15 patients with type 2 diabetes." (PMID 27548138, 2016). "Interestingly, hepatic CMKLR1 tends to be increased in type 2 diabetes patients in both genders and upregulation is significant in the whole cohort." (PMID 27548138, 2016). "Whether hepatic CMKLR1 is associated with metabolic diseases such as hypercholesterolemia or type 2 diabetes has not been evaluated to our knowledge so far." (PMID 27548138, 2016). "Thus, an agonist of CMKLR1 might be effective in the treatment of type 2 diabetes." (PMID 25699203, 2015). "This suggests that elevated CMKLR1 mRNA in the liver of these patients is not necessarily related to NASH which has a higher prevalence in type 2 diabetes." (PMID 27548138, 2016).
viral infection (5 papers, 2011 to 2021). "Protein levels of the chemerin receptor CMKLR1 strongly declined in the tumors of NAFLD patients and patients with unclear disease etiology but not in patients with viral infections." (PMID 33066325, 2020).
Cognitive impairment (4 papers, 2019 to 2023). Abnormal cognition is characterized by deficits in thinking, reasoning, or remembering. "CMKLR1 deficiency increases Aβ deposits in AD mice, reduces mortality, and improves the cognitive impairment of AD mice." (PMID 36012305, 2022).
lung fibrosis (4 papers, 2022 to 2025). "To address this limitation, we performed an exploratory study to determine CMKLR1 expression in lung tissues from patients with various causes of pulmonary fibrosis." (PMID 38896611, 2024). "Genetically engineered RARRES2−/− (chemerin-deficient) and CMKLR1−/− mice have been used to study metabolic and inflammatory diseases, but there is a paucity of data examining their response to bleomycin- or silica-induced lung fibrosis." (PMID 41154697, 2025). "Preclinical studies have demonstrated that CMKLR1 antagonists or chemerin modulators can alleviate pulmonary fibrosis in animal models." (PMID 41154697, 2025). "In bleomycin-induced pulmonary fibrosis in mice, chemerin and its receptor, CMKLR1, are markedly upregulated in lung tissue, largely under the influence of oxidative stress and pro-inflammatory cytokines characteristic of fibrosis." (PMID 41154697, 2025). "By analyzing single-cell RNA sequencing datasets, we demonstrated CMKLR1 expression as a transient signature of monocyte-derived macrophages (MDMφ) enriched in patients with idiopathic pulmonary fibrosis (IPF)." (PMID 38896611, 2024). "To determine the potential of CMKLR1-targeted PET to predict the progression of pulmonary fibrosis, we conducted a longitudinal study in which mice underwent PET/CT at week 1 postbleomycin and were followed until week 4 to assess the extent of fibrosis." (PMID 38896611, 2024). "CMKLR1 is an imaging biomarker of the inflammation-fibrosis axis by identifying a macrophage subset enriched in lung fibrosis." (PMID 38896611, 2024). "Consistently, we identified MDMφ as the major driver of the uptake of CMKLR1-targeting peptides in a murine model of bleomycin-induced lung fibrosis." (PMID 38896611, 2024). "Furthermore, CMKLR1-targeted positron emission tomography in the murine model enabled quantification and spatial mapping of inflamed lung regions infiltrated by CMKLR1-expressing macrophages and emerged as a robust predictor of subsequent lung fibrosis." (PMID 38896611, 2024). "In regard to chemerin signaling, a study examining lung fibrosis after bleomycin exposure using CMKLR1-deficient mice found that the lack of CKMLR1 expression resulted in an increase in neutrophil, but a decrease in NK cell, recruitment to the lung as well as an increase in lung fibrosis." (PMID 40564073, 2025). "Consequently, the application of CMKLR1-targeted PET may extend beyond pulmonary fibrosis to various inflammatory lung diseases; hence, it is imperative to consider the unique context of the underlying disease for a better understanding of the implications of the uptake of CMKLR1-targeting tracers." (PMID 38896611, 2024). "CMKLR1-targeted PET may also serve as a tool for mechanistic studies, shedding light on the role of accumulated MDMφ in sustaining inflammation beyond the resolution of acute injury and driving progressive lung fibrosis." (PMID 38896611, 2024).
preeclampsia (4 papers, 2022 to 2024). Preeclampsia is a hypertensive disorder of pregnancy that is characterized by new-onset hypertension with proteinuria presenting after 20 weeks of gestation, and depending on mild or severe forms may initially present with severe headache, visual disturbances, and hyperreflexia. "Chemerin may be a novel biomarker of preeclampsia, and inhibition of the chemerin/CMKLR1 pathway may be a promising new therapeutic strategy for the treatment of preeclampsia." (PMID 37964253, 2023).
rheumatoid arthritis (4 papers, 2011 to 2024). A chronic, systemic autoimmune disorder characterized by inflammation in the synovial membranes and articular surfaces. "Last, our exploratory histological analysis of lung specimens suggests that CMKLR1 is a relevant inflammatory biomarker in a wide range of fibrotic lung diseases in addition to IPF, such as sarcoidosis, scleroderma, rheumatoid arthritis, and coal worker pneumoconiosis." (PMID 38896611, 2024).
coronary atherosclerosis (3 papers, 2014 to 2022). Atherosclerosis of the coronary vasculature. "In contrast, chemerin, which can bind to the G protein-coupled receptor (CMKLR1), is associated with immune response and the metabolism of glucose and lipids, and its expression levels are reportedly positively associated with coronary atherosclerosis." (PMID 36345357, 2022). "It was reported that foam cell CMKLR1 expression strongly and positively correlates with aortic atherosclerosis, but only marginally with coronary atherosclerosis." (PMID 34299034, 2021). "A marginally non significant correlation was observed between coronary foam cell CMKLR1 expression and coronary atherosclerosis (r=0.317, p=0.056) and remained non significant when controlling for age (ρ=0.290, p=0.086) and BMI (ρ=0,328, p=0.051)." (PMID 24779513, 2014). "Coronary atherosclerosis was also correlated with chemerin and CMKLR1 expression in coronary samples." (PMID 24779513, 2014).
depression (3 papers, 2019 to 2021). "The modification of Cmklr1 was shown to implicate depression in the prefrontal cortex and hippocampus responding to chronic restraint stress (CRS)." (PMID 33898422, 2021). "CMKLR1 is detected in the hippocampus and prefrontal cortex, two critical brain regions involved in the pathology of depression." (PMID 31718027, 2019).
endometriosis (3 papers, 2021 to 2024). The growth of functional endometrial tissue in anatomic sites outside the uterine body. "Regarding the endometriosis group, there are evidence relating one of the mutated genes (CMKLR1) with endometriosis and/or the endometrium." (PMID 34318471, 2021). "Abnormal chemerin/CMKLR1 axis underlies the pathological mechanisms of certain diseases including cancer and inflammatory diseases, but its role in endometriosis remains unknown." (PMID 36523492, 2022). "Interestingly, one of the mutations found in one endometriosis patient was related to a gene (CMKLR1) already associated with endometriosis, endometrial function, and initial gestational development." (PMID 34318471, 2021). "Small molecules that selectively inhibit the chemerin receptor CMKLR1 have also been reported to inhibit endometriosis growth, and chemerin signaling inhibitors are expected to serve as orthologous cancer therapeutics." (PMID 38238841, 2024). "Herein, our results showed that chemerin and CMKLR1 are up-regulated in endometriotic lesions by analyzing the human endometriosis database and murine model." (PMID 36523492, 2022). "Taken together, using a combination of bioinformational, genetical, pharmacological, and histological analysis approaches, we show here that the chemerin/CMKLR1 axis is crucial for endometriosis development." (PMID 36523492, 2022). "Most importantly, 2-(α-naphthoyl) ethyltrimethylammonium iodide (α-NETA), a small molecule antagonist for CMKLR1, was evidenced to exhibit profound anti-endometriosis effects (anti-growth, anti-mesenchymal features, anti-angiogenesis, and anti-inflammation) in vitro and in vivo." (PMID 36523492, 2022). "Additionally, we provide evidence that CMKLR1 antagonist α-NETA exhibits profound anti-endometriosis effects (anti-growth, anti-mesenchymal features, anti-angiogenesis, and anti-inflammation) in vivo." (PMID 36523492, 2022). "This study highlights that the chemerin/CMKLR1 signaling axis is critical for endometriosis progression, and targeting this axis by α-NETA may provide new options for therapeutic intervention." (PMID 36523492, 2022). "In this article, we found that chemerin and CMKLR1 were aberrantly upregulated in endometriosis." (PMID 36523492, 2022). "Supported by Banu SK and coworker’s proposal that dual inhibition of PI3K/Akt and MAPK/ERK is indispensable for the suppression of endometriosis establishment and progression, we provide molecular insights into the therapeutic effects of targeting chemerin/CMKLR1 axis by α-NETA in endometriosis." (PMID 36523492, 2022). "In order to explore the signaling transduction mechanisms of chemerin/CMKLR1 in endometrial stromal cells, two critical signaling pathways (PI3K/Akt and MAPK/ERK) known to implicate in endometriosis establishment and development were examined." (PMID 36523492, 2022). "Accordingly, herein, we endeavored to study the role of the chemerin/CMKLR1 axis in endometriosis and to access whether antagonizing this axis by α-NETA could ameliorate the endometriosis progression." (PMID 36523492, 2022). "In 2015, literature reported that chemerin and CMKLR1 expression were aberrantly up-regulated in the ovarian endometrioma tissues relative to the eutopic endometrial tissues, but the pathological mechanisms by which the chemerin/CMKLR1 axis modulates endometriosis remain lacking." (PMID 36523492, 2022).
Hyperinsulinemia (3 papers, 2019 to 2021). An increased concentration of insulin in the blood. "Indeed, as hyperinsulinemia in the IR states, the high chemerin levels found in obese women could be a compensatory response to the lack of CMKLR1 in GCs." (PMID 31382403, 2019).
liver disease (3 papers, 2014 to 2025). "Since severities of liver disease may influence chemerin/CMKLR1 axis in the liver tissues, we believe that investigation on guts may help to get insight the role of chemerin/CMKLRS axis on NAFLD." (PMID 36624417, 2023).